CTNNB1 (catenin beta 1)
Diseases named in the same sentence as CTNNB1 in open-access papers (continued):
Sharing a sentence is not in itself a finding about the gene and the disease.
tumor (continued). "In terms of tissue-based studies, CTNNB1-mutated HCC has been reported to induce an immune-cold tumor microenvironment (TME) with a lack of immune cell infiltration, promoting resistance to ICI monotherapy." (PMID 40447887, 2025). "Accordingly, analysis of the RNA sequencing data showed relatively higher levels of expression of β-catenin and Wnt/β-catenin targets in tumours with either the CTNNB1 p.I35T or FBXW11 p.F517S mutation compared to those without these mutations." (PMID 40389436, 2025). "Loss-of-function mutations in the oncosuppressor APC, mutations in CTNNB1 (β-Catenin gene), and the excessive presence of Wnt ligands in the tumor microenvironment (TME) disrupt these regulatory mechanisms, resulting in uncontrolled tumor growth." (PMID 40722631, 2025). "have demonstrated ACCs with an activating CTNNB1 mutation to exhibit higher expression of LEF-1 compared to non-tumour adrenal samples and ACCs without CTNNB1 mutation." (PMID 40130164, 2025). "The CTNNB1-mutant (p.I35T) tumor in our series was morphologically distinct, displaying more fibrous stroma, focal glandular differentiation, less primitive cytologic features, a lower mitotic rate, and a lower Ki-67 proliferative index compared to the FGFR2-mutant tumors." (PMID 40906279, 2025). "There is evidence of concordance between TERTp and CTNNB1 mutations in HCC, suggesting a cooperative role in hepatocarcinogenesis, as studies indicate that their co-occurrence may promote tumour development and progression." (PMID 40650279, 2025). "Clinical validation in HCC patients confirmed successful CTC detection, and tumor-specific CTNNB1 mutations were identified in CTC-derived DNA but not in matched plasma cfDNA." (PMID 41203725, 2025). "Mutations in TERTp and CTNNB1 exon 3 are frequently observed in HCC and have been reported to co-occur in some cases, potentially due to complementary oncogenic mechanisms, although this association appears to vary across tumor subtypes and populations." (PMID 40243493, 2025). "CTNNB1-activated tumours were found within all spatial immunotypes." (PMID 39349005, 2025). "Furthermore, a correlation has been demonstrated between elevated ETBF levels and the increased expression of axis inhibitor (AXIN) and catenin beta 1 (CTNNB1) in tumor tissues." (PMID 40332367, 2025). "The tumour suppressor APC is part of the destruction complex that regulates β-catenin, and in CRCs, APC inactivating mutations are almost always mutually exclusive with CTNNB1 activating mutations." (PMID 40389436, 2025). "Therefore, we investigated the expression of WNT family genes and the CTNNB1 gene encoding β-catenin, a key mediator of canonical WNT signaling, in the tumor niche." (PMID 40650009, 2025). "The expression of β-catenin protein encoded by CTNNB1 was also higher in pre-neoadjuvant IMPC tumor samples than that in the non-IMPC samples." (PMID 40821778, 2025). "The non-proliferation class comprises well-differentiated tumours, often harbouring CTNNB1 (β-catenin) mutations and displaying metabolic or hepatocytic signatures with low AFP levels." (PMID 41301037, 2025). "Interestingly, Zone 1/2 CTNNB1 MUT (GS+) hepatocytes were the most proliferative tumor cell population, with the most cells in S and G2M cell cycle phases." (PMID 40442146, 2025). "Notably, in patient 5, a tumor rebiopsy revealed a significant increase in CTNNB1 mutation frequency (0.4%-30.0%), alongside an increase in EGFR allele frequency (27/28% to 62/62%), correlating with a higher tumor cell content (40% v 70% at rebiopsy)." (PMID 40768678, 2025).
tumor (continued). "Therefore, molecular characteristics based on known genetic variants such as CTNNB1 and BRAF9 can be identified, and the mechanisms via which cell-cell interactions in the TME influence tumor biology and disease progression can be understood." (PMID 39483146, 2024). "CTNNB1 mutations in HCC are often monoallelic, leaving a wild-type allele in tumor cells." (PMID 39008536, 2024). "Notably, tumor growth was significantly inhibited after EnCore-R/CTNNB1 treatment in WNT-driven colorectal and HCC models." (PMID 39253139, 2024). "Interestingly, Zone 1/2 CTNNB1 MUT [GS+] hepatocytes were the most proliferative tumor cell population, with the most cells in G2/M cell cycle phase." (PMID 39711542, 2024). "Notably, the nuclear staining can be patchy and focal, with nearly half of CTNNB1 mutant cases showing nuclear staining in only 5–10% of tumor cells." (PMID 38539494, 2024). "Moreover, we performed the same evaluation for tumor cells upon knockdown of CTNNB1, which has been shown to positively regulate ALDH1A1 expression." (PMID 38169509, 2024). "CTNNB1 exhibited high expression levels in both tumor and normal samples." (PMID 38240703, 2024). "As CTNNB1 mutations are extremely rare in ICC patients, we postulated that β-catenin signaling is activated via other pathways, for example, the WNT ligands from the tumor microenvironment." (PMID 38926350, 2024). "Interestingly, ILCs, particularly ILC3s, in the inflammatory or tumor microenvironment of patients with IBD or CRC expressed significantly higher levels of CTNNB1, and Wnt/β-catenin downstream genes TCF7, VEGFA and MYC, as compared with control tissues." (PMID 38561332, 2024). "Point mutations of CTNNB1 and AXIN1, likely activating the WNT pathway, also were restricted to invasive or metastatic stages often contributing to genetically heterogeneous subclones within the primary tumor." (PMID 39034322, 2024). "Furthermore, the expression of EMT genes and oncogenes, including Mmp3, Mmp7, Mmp8, Fn1, Vim, Foxc2, Ctnnb1, Lgr5, Axin2, cMyc, Ccnd1, and Yap1, was significantly high in the tumor of cohoused Nlrp12–/– compared with WT mice." (PMID 37581937, 2023). "We used our preclinical tumor model to extend our in vitro findings and confirm that the therapeutic inhibition of Wnt/β-catenin significantly inhibits the growth of tumors harboring a GOF CTNNB1 mutation." (PMID 37509222, 2023). "During or after neoadjuvant chemotherapy, 33–36% (5/15 to 5/14, as one case was lacking tumor CTNNB1-mutation confirmation with Sanger sequencing) of samples had detectable CTNNB1 variants, with a mean VAF of 3.5% (ranging from 0.3% to 6.3%)." (PMID 38201440, 2023). "In Mcl-1Δhep tumours, Hras and Kras proto-oncogenes were not mutated and Ctnnb1, Apc, Braf, Egfr, and Pten were not frequently mutated." (PMID 37663116, 2023). "miR-495-3p is a tumor suppressive miRNA that targets CTNNB1 and inhibits GC progression." (PMID 37386429, 2023). "Previously, it was reported that miR17-5p could repress RBL2, also named P130, to release activating transcription factor E2F4 or CTNNB1, which promoted tumor progression by inducing activation of multiple targeted genes like CCND1 and CCNE1 etc.." (PMID 37506248, 2023).
tumor (continued). "Notably, our findings revealed a significant relationship between a high amount of B. fragilis and high levels of AXIN and CTNNB1 expressions in the tumor tissues." (PMID 37644520, 2023). "In this study, we demonstrate that western diet in DIAMOND mice induces such exclusion of Ctnnb1 exon 3 in a large subset of the tumours, and that this is not accompanied by mutations in the corresponding genomic region." (PMID 37907668, 2023). "No somatic mutations were detected in the Ctnnb1 exon 3 region in 6 out of these 8 tumours displaying exon 3 exclusion." (PMID 37907668, 2023). "In the genomic analysis of LUAD, the levels of CTNNB1 were higher in patients with metastatic stages 3 and 4 (46%, 7 tumors/15 total) than in those with tumor stage 1 (27%; 8 tumors/29 total), indicating that β-catenin and PLK1 are markedly expressed in metastatic NSCLC, especially in LUAD." (PMID 36793862, 2023). "Moreover, we simulated different β-catenin acetylation state by transfecting CTNNB1 KD tumor cells with CTNNB1-WT, mutant K49Q (acetylation-mimetic) and K49R (deacetylation-mimetic) to compare their effects on cellular metabolism." (PMID 37063423, 2023). "In two of these three cases, the tumor CTNNB1 variants were distinct (SJWLM066776 CTNNB1 p.T41A vs. p.S45del, SJWLM051028 CTNNB1 p.S45P vs. p.S45del) and in the remaining case (SJWLM066780) the CTNNB1 p.S45F variant was shared in both paired tumors." (PMID 38110397, 2023). "Regarding non-inflamed class, the excluded subclass had the lowest tumor immune cell infiltration and a higher incidence of CTNNB1 mutations than the intermediate subclass (93% vs. 17%; p = 5.55 × 10−12)." (PMID 37190239, 2023). "Given that CD142 is enriched in desmoid tumor CTNNB1 mutant cells, targeting CD142 in desmoid tumors for cytotoxic drug delivery may offer a promising therapeutic option." (PMID 37377751, 2023). "Among them, ERBB4 and NPM1 are presumably involved in cSCC tumorigenesis; in addition, GNAQ, GNAS, JAK2, NRAS, IDH2, and CTNNB1 may be related to tumor metastasis." (PMID 36780540, 2023). "Additionally, we found that the high-CTNNB1-expression group exhibited an enrichment of activation signals pertaining to tumor cell proliferation and metastasis-related pathways (E2F targets, Epithelial-mesenchymal transition)." (PMID 37881428, 2023). "We studied the transcription of WNT and CTNNB1 (β-catenin) genes in MM-MSCs to find out whether their transcription occurs in MSCs of a healthy and tumor HN." (PMID 37239457, 2023). "Indeed, we found significant regulation in genes involved in this CTNNB-1 signature, particularly in S2 tumours." (PMID 35301339, 2022). "Considering the NSMP group, it may be stratified based on histological (i.e., tumor grade and histotype, LVSI, and depth of myometrial invasion), immunohistochemical (i.e., L1CAM expression), or molecular (i.e., CTNNB1 mutation) features." (PMID 35463299, 2022). "Some studies, in line with ours, recommended the use of CTNNB1 as a marker of tumor progression." (PMID 36140796, 2022). "Thus, if a gene such as CTNNB1, the gene of the WNT and cross-linked pathways that most contributes to PC3 or tumor aggressiveness, represents 14.02% of PC3, it, indeed, represents only 2.6% of the total variation." (PMID 35565454, 2022). "The NSMP group may further be stratified based on histological (i.e., tumor grade and histotype, LVSI, depth of myometrial invasion), immunohistochemical (i.e., L1CAM expression), or molecular (i.e., CTNNB1 mutation) features." (PMID 35463299, 2022). "Notably, the results showed that GBAs already have some tumour‐related gene mutations, such as CTNNA2, CTNNB1, and KChIP3, which regulate the cell cycle and apoptosis." (PMID 35075805, 2022). "Polyclonality in Ctnnb1 was found in tumor samples and cfDNA in this model." (PMID 36313038, 2022). "We performed Sanger sequencing of CTNNB1 exon three in the tumor DNA from all patients." (PMID 35053583, 2022).
tumor (continued). "Obviously, the cadherin binding related genes including CTNNB1, CDH1, ITGA6, KRT18, and PROM1 were significantly associated with EpCAM, which also implied that EpCAM could play a role in tumor metastasis." (PMID 35517503, 2022). "CTNNB1-mutated HCC has been reported to induce an immune-cold tumor microenvironment (TME) lacking immune cell infiltration and promote resistance to ICI monotherapy." (PMID 35884434, 2022). "ACSL3 has a favorable correlation with CTNNB1, a recognized tumor-promoting gene." (PMID 36338658, 2022). "Moreover, β-catenin signaling within tumor cells can shape the immune microenvironment around them, as it was shown that melanoma cells with elevated levels of CTNNB1 in the nucleus express IL10 and IL12, which promote immunosuppression." (PMID 36612190, 2022). "Another study showed how the identification of CTNNB1 alterations, along with ARID1A mutations, could represent an effective way to characterize the tumor aggressiveness of the heterogenous NSMP group." (PMID 35205661, 2022). "Analysis of triple mutants (PBCre4 Ctnnb1+/Δex3Ptenfl/fl; K-Ras+/G12V) revealed these three genetic alterations could synergize to drive aggressive tumor progression relative to double or single mutants via increased mTORC1 activity." (PMID 35204808, 2022). "Besides, this study also suggested that APA profiles of some clinically actionable genes varied greatly among different tumor types, such as CTNNB1 and PIK3R1." (PMID 35487956, 2022). "The CTNNB1 A45_E54del mutation that was detected in T1c but no longer detectable in T2b was detected in the cfDNA, suggesting the mutation remained in the tumor." (PMID 35263170, 2022). "Apart from CTNNB1, we’ve identified several cancer-related gene mutations, including PML, HSP90AA1, BAZ1A, ARHGAP5, LHFPL6 in the primary tumor of HB, which may also contribute to the carcinogenesis of HB." (PMID 35860547, 2022). "All tumours carry exon 3 deletions of CTNNB1, conferring WNT-independent activity on β-catenin." (PMID 34916592, 2022). "35% of tumor specimens with APC/CTNNB1 genetic aberrations did not harbor either BRAFV600/K601 or NRASQ61 mutations compared with 50% of tumor specimens without." (PMID 34986841, 2022). "One CTNNB1 wild-type tumor gained WNT activation due to homozygous FBXW7 deletion." (PMID 36181537, 2022). "The CTNNB1 mutation and high mTOR activity is compatible with SNU398 originating from a R3 tumor." (PMID 36309506, 2022). "Moreover, CTND1 is involved in the Wnt/beta-catenin/CTNNB1 signaling pathway by regulating cell proliferation, migration, and differentiation of endothelial cells in tumor growth." (PMID 36011023, 2022). "Gain-of-function mutation of CTNNB1 contributes to resistance of ICI monotherapy through the framework of non-T-cell-inflamed tumor microenvironment." (PMID 35711837, 2022).
tumor (continued). "Censoring for any mutation in a panel of 460 genes associated with human cancers found a CAN ➞ CT/GN mutation with a high VAF in Ctnnb1 and in Spen in one Kras/Braf mutation-negative tumor each, but these mutations were not conserved in human cancers." (PMID 35482806, 2022). "Patients with CTNNB1 exon 3 mutation had a mean DFS of 73.79 ± 41.59 (range, 10–144) months compared with 81.00 ± 44.32 (range, 0–174) months for patients with wild-type CTNNB1 exon 3 tumours (p = 0.010)." (PMID 34420090, 2021). "In our series, half of the tumours harbouring CTNNB1 mutation and absent TMA beta-catenin expression showed focal nuclear expression in the whole slide." (PMID 34420090, 2021). "It is well known that up to 80% of sporadic lesions, regardless of tumour location, harbour mutations in the CTNNB1 gene, which encodes the β-catenin protein." (PMID 33914771, 2021). "Following a translational route, the team that conducted these experiments also obtained and sequenced tumor DNA from 13 patients that had underwent clinical FCH PET/CT and found mutated CTNNB1 in 6/7 patients with FCH-positive tumors and wild-type CTNNB1 in 6/6 patients with FCH-negative tumors." (PMID 33553649, 2021). "In addition, it was found that coexpression of mutant CTNNB1 with EMX1 or EMX2 individually or both EMX genes (EMX1 + EMX2) enabled reversion to a more aggressive tumor phenotype due to increased cell proliferation and clonogenicity." (PMID 34364391, 2021). "A recent report showed that proteins involved in different metabolic activities such as drug metabolism, amino acid metabolism, glycolysis and gluconeogenesis are enriched in CTNNB1 mutant tumours, indicating that it is closely related to metabolic reprogramming." (PMID 33300278, 2021). "The resected tumor was positive for the CTNNB1 mutation, while there was no tissue available from the ablated tumor." (PMID 33827453, 2021). "HCC-adjacent tissues from the 18 CTNNB1-mutation-positive patients contained no detectable mutations, suggesting that the CTNNB1 mutations detected in the tumor tissues were somatic rather than germline." (PMID 34441409, 2021). "To explore the potential of prime editors to drive tumor formation in vivo, we delivered PE2 or PE2*, a pegRNA used for installation (via C-to-T) of the oncogenic S45F mutation in Ctnnb1, and a nicking sgRNA to the livers of adult FVB mice (n = 4/group) by hydrodynamic tail vein injection." (PMID 33837189, 2021). "WNT tumours are rare in young children (peak around 9 years of age), and are associated with a WNT profile (on expression or DNA-methylation-based profiling), CTNNB1 mutation, isolated chromosome 6 loss and nuclear localisation of the ß-catenin protein (encoded by CTNNB1)." (PMID 34885186, 2021). "CTNNB1 mutations which induce excessive activation of Wnt-β-catenin pathway in HCC play a crucial role in regulating tumor cell proliferation and survival and in tumor angiogenesis." (PMID 34568069, 2021). "In 2017, based on the demonstration that each of the tumor’s components harbors a distinct somatic mutation (i.e., BRAF mutation in the epithelial component and CTNNB1 mutation in the mesenchymal component), we proposed the term “papillary thyroid carcinoma with desmoid-type fibromatosis” (PTC-DTF)." (PMID 34503292, 2021). "The study demonstrated that β-catenin signaling (CTNNB1) mediated immune escape of tumors by preventing recruitment of CD103+ DCs leading to an early failure of the cancer immune cycle that inhibited generation of robust tumor-specific T cell activity." (PMID 34209393, 2021).